AHR (aryl hydrocarbon receptor)
Diseases named in the same sentence as AHR in open-access papers (continued):
Sharing a sentence is not in itself a finding about the gene and the disease.
tumor (continued). "Thirdly, the production of kynurenine, resulting from catabolism of tryptophan, activates transcription of the aryl hydrocarbon receptor (AHR), leading to differentiation of Foxp3+ Treg cells which suppress of anti-tumor responses." (PMID 31430935, 2019). "Reported Src-mediated crosstalk between AhR and EGFR signaling pathways demonstrated an important link between AhR canonical function and TCDD-mediated tumor promotion." (PMID 31328183, 2018). "As these enzymes play critical roles in tumor initiation and promotion, it was proposed that the UVB-activated AHR contributes to photocarcinogenesis." (PMID 30013037, 2018). "ChIP qPCR of intestinal epithelial cells established Rnf43 as a direct target of AHR, suggesting that this tumor suppressor, which acts in a complex with ZNRF3, is transcriptionally regulated by AHR." (PMID 30119997, 2018). "In the tumor microenvironment (TME), kynurenine (KYN) accumulation, an endogenous metabolites of tryptophan catabolism, acts as a ligand and activates AHR, which translocates to the nucleus and results in the transcription of target genes." (PMID 29301348, 2018). "Interaction between the AhR and TCDD and other ligands contribute to cancers derived from B-cell lineages by affecting the growth and survival of cells via the tumor microenvironment." (PMID 29487603, 2018). "Knockdown of the AHR repressor (AHRR), a putative tumor suppressor, increases anchorage-independent growth and tumor formation in lung cancer xenografts." (PMID 29735912, 2018). "The binding of Kyn to AhR promotes naive CD4+ T cell differentiation into Treg cells, which contributes to an immunosuppressive tumor microenvironment." (PMID 30068361, 2018). "Similar results have been demonstrated in the studies of Villano and colleagues and Haque and coworkers, suggesting that activation of an AhR pathway can enhance MMP expression and result in tumor invasiveness." (PMID 29487603, 2018). "Furthermore, analysis of an array of invasion-associated genes after AHR knockdown suggested plausible mechanisms through which the AHR drives tumor invasion, further supporting the conclusion that AHR inhibition, at least in these TNBC and IBC lines, reduces tumor aggression." (PMID 29735912, 2018). "Elevated AhR and CYP1B1 gene expression reported before tumor formation in a rat model of mammary tumorigenesis suggested differential CYP1B1 regulation by a constitutively active AhR." (PMID 28671964, 2017). "AHR has also been reported to activate transcription of the cyclin-dependent kinase inhibitor CDKN1B (p27) gene, a tumour suppressor that inhibits cyclin–cyclin-dependent kinase (CDK) interactions and maintains Rb in its hypophosphorylated state." (PMID 28649092, 2017). "Depletion of cytoplasmic AHR content represents a potential switch for EMT, thereby leading to the scattering of tumor cells." (PMID 27752740, 2017). "In 8 randomly selected HCC samples obtained from patients in the high AHR group, the increased HDAC8 expression correlated with the expression pattern of AHR when compared with those of paired tumor-adjacent, normal tissues." (PMID 27283490, 2017). "UVB-induced AhR activation upregulates suppression of reversible tumor promotion before tumor the RAF-MEK1/2-ERK1/2 signaling pathway via c-Src-dependent EGFR activation, and when AhR is activated, it upregulates its specific target gene, cyp1a1." (PMID 29285309, 2017). "We first measured the gene expression from tumor tissues, including SOD2, AHR and VEGF, for both mRNA and protein levels." (PMID 29212263, 2017). "The expression correlation between AHR and HDAC8 was further verified by immunofluorescence staining of HCC patient tumor tissue." (PMID 27283490, 2017). "We then found that the expression of both AHR and HDAC8 was significantly upregulated in both HCC cell lines and tumor tissues compared to human normal hepatocytes and matched non-tumor tissues." (PMID 27283490, 2017).
tumor (continued). "The anti-tumor effects of IDR are mediated through the inhibition of DNA transcription to RNA and activation of the aryl hydrocarbon receptor (AhR)." (PMID 28025493, 2016). "Moreover, the pro-tumoral phenotype caused by AhR depletion in the tumor cell (cell autonomous) required AhR expression in the microenvironment as AhR-/- mice could not support tumor growth and metastatization of AhR-depleted cells." (PMID 27243009, 2016). "Collectively, these studies highlight the importance of the AhR in IDO1 and/or TDO2 expressing tumours and emphasize the role that autocrine production of inflammatory cytokines plays in tumour survival and growth." (PMID 26646699, 2016). "Immunohistochemistry (IHC) revealed that the number of stained AHR and SPHK1 cells was reduced in the primary tumor." (PMID 27129165, 2016). "The aryl hydrocarbon receptor (AHR) is a ligand-activated transcription factor mediating the toxicity and tumor-promoting properties of dioxin." (PMID 26392334, 2015). "Here, we show that by microarray and IPA analysis in NB tumor samples, the regulation of MYCN expression is closely related to AHR expression." (PMID 24586395, 2014). "Further, B[α]P serves as ligand with the aryl hydrocarbon receptor (AHR), shown to be rate-limiting step in B[α]P-induced tumor formation." (PMID 25054229, 2014). "Hsieh demonstrated that phthalates stimulated the aryl hydrocarbon receptor (AhR) and triggered the cyclic AMP (cAMP)/PKA/CREB1 pathway, which emanated from the phthalated-induced AhR promoted tumor genesis of ER-negative breast cancer." (PMID 23469012, 2013). "The activation of AhR by a typical agonist, 2,3,7,8-tetrachlorodibenzo-p-dioxin (TCDD), has been shown to promote tumor formation in both liver and skin." (PMID 24330582, 2013). "To explore the relationship between promoter methylation and gene expression in primary tumours we performed a qRT-PCR analysis of SOX9, HOXA9, AHR, ROBO1, and NR2F2 in a series of 36 MCL." (PMID 21603610, 2011). "The subsequent analysis in primary MCL identified five genes (SOX9, HOXA9, AHR, NR2F2, and ROBO1) frequently methylated in these tumours." (PMID 21603610, 2011). "This framework reveals both canonical and previously unrecognized lineage-restricted dependencies within highly plastic tumor and NEPC states, including a therapeutically targetable dependency on the aryl hydrocarbon receptor (AHR) in a novel hybrid stem-like/ASCL1 population." (PMID 42146571, 2026). "In many tumours, IDO1 is highly expressed, AhR levels are also elevated." (PMID 40040508, 2025). "If essential amino acids drop tenfold similar to glucose, IDO1 in the tumor environment could elevate Kyn tenfold, reaching the competitive level for SLC7A5 and effectively activating AhR." (PMID 40103267, 2025). "Our findings reveal that AHR suppresses CSC formation triggered by low-dose As3+ (0.5 μM) via transcriptional repression of TOX, a high mobility group box DNA binding protein that play a critical role in T cell exhaustion within tumor immunology." (PMID 40303305, 2025). "We conclude that lack of AhR activation by dietary ligands specifically in macrophages does not affect the efficacy of anti-PD1 therapy in this tumor model." (PMID 41331250, 2025). "However, another AhR agonist, MEHP, competitively antagonizes TCDD, reducing its ability to promote tumor EMT." (PMID 40103267, 2025). "Additionally, the aryl hydrocarbon receptor (AHR), which can be activated by tryptophan-derived ligands, contributes to an immunosuppressive and tumor-permissive environment." (PMID 41375042, 2025). "Furthermore, we found that both AhR and c‐MYC inhibition in tumor cells increased level of STAT3 phosphorylation, which was required for I3A‐induced immunogenicity." (PMID 40583248, 2025). "Next, we reasoned that AhR and c‐MYC might be the two key factors suppressing tumor immunogenicity, which can be reversed by I3A treatment." (PMID 40583248, 2025).
tumor (continued). "To directly address whether AhR was required in T cells for response to anti-PD1 therapy, we assessed tumor growth in WT and Lck*AhRΔ mice, fed on I3C diet." (PMID 41331250, 2025). "Together, our findings demonstrate that IL4I1+ TAMs and TDO2+ myCAFs synergistically establish an immunosuppressive, ferroptosis-resistant niche via AhR signaling in solid predominant LUAD and offer promising therapeutic strategies to reprogram the tumor microenvironment." (PMID 41431173, 2025). "Additionally, UCHL3 stabilizes the aryl hydrocarbon receptor (AHR) via deubiquitination, leading to increased PD-L1 expression and enhanced immune evasion in tumor cells." (PMID 40710178, 2025). "The main enriched hallmarks in AHR-high vs. AHR-low tumours found irrespective of ER status were related to immune response." (PMID 40646277, 2025). "This creates an increased ratio of kynurenine to tryptophan, which is proposed to contribute to an immunosuppressive tumour microenvironment, in part (but not entirely) through activity of kynurenine on the aryl hydrocarbon receptor (AhR)." (PMID 40751253, 2025). "No other statistically significant differences according to AHR genotype were observed, including tumour-specific cytoplasmic or nuclear AhR protein levels." (PMID 40646277, 2025). "AhR‐WT and AhR‐CA re‐expression in AhR‐knockdown cells lowered I3A‐induced tumor immunogenicity, but AhR‐dNLS did not." (PMID 40583248, 2025). "By engaging receptors such as GPR41/43 and aryl hydrocarbon receptor (AhR) or altering epigenetic programs through histone deacetylase (HDAC) inhibition, these metabolites remodel immune niches both locally and at distant tumor sites." (PMID 41339918, 2025). "Our previous study identified a marked reduction in AHR expression in peripheral blood mononuclear cells (PBMCs) from patients with more progressive PDAC, indicating systemic dysregulation of the AHR pathway beyond the tumor site." (PMID 41357201, 2025). "TDO promotes tumor cell migration and invasion through the TDO2-Kyn-AhR pathway." (PMID 41282989, 2025). "The interplay between AHR and lncRNAs may have important clinical implications in HCC treatment, particularly through its influence on tumor progression and metabolic reprogramming." (PMID 40248203, 2025). "Next-wave interventions pair metabolic brakes with programmed cell death protein 1 (PD-1)/programmed cell death ligand 1 (PD-L1) or heat shock protein 90 (HSP90) blockade, deploy AhR antagonists, phytochemicals, or AhR inhibitors such as BAY2416964 to restore immunity and curb tumor growth." (PMID 40868271, 2025). "Thus, Trp depletion and Trp–Kyn–AHR-related metabolites contribute to CD8+ T cell malfunction and tumor immune evasion." (PMID 39950085, 2025). "Additionally, PM2.5 has been reported to activate the aryl hydrocarbon receptor (AhR), which promotes EGFR signalling and upregulates oncogenic factors such as TMPRSS2 and IL18, contributing to tumour progression." (PMID 40559957, 2025). "Conversely, the AhR agonist, 6-formylindolo[3,2-b]carbazole (FICZ), increased the proportion of TRAIL+ LrNK cells by upregulating FoxO1 expression, thereby enhancing local anti-tumor immune activity." (PMID 39893278, 2025). "Another study showed that the tryptophan metabolite indole activates the AHR and also promotes the conversion of TAMs to an immunosuppressive phenotype in pancreatic ductal adenocarcinoma and inhibits the accumulation of CD8+ T cells in the tumor." (PMID 40066456, 2025). "Since cellular dormancy requires high signaling, the low expression of IDO1 and AhR in tumor cells fails to generate sufficient p27 and other dormancy‐related proteins, leading to a different response to IFN‐γ." (PMID 40103267, 2025). "AhR expression was not directly correlated with the tumor stage, grade, or metastasis, presenting a different pattern from those found previously." (PMID 38680496, 2024).
tumor (continued). "Expression and functional role of AhR, CYP1A1 and CYP1B1: Animal and clinical data provide evidence for the role of AhR in gastric tumorigenesis, implicating the receptor in the regulation of tumor growth, EMT, migration, invasion, and cancer aggression." (PMID 39200369, 2024). "While induction of AhR activity is required to stimulate CYP-induced metabolic activation of 1, 2 and 3, the magnitude of AhR induction by the BBQ analogues did not directly correlate with the potency of growth inhibition or to tumour type selectivity." (PMID 38974991, 2024). "Moreover, IL4I1 can stimulate the expression of AHR target genes TIPARP and CYP1B1 in CD8+ T cells, contributing to the suppression of CD8+ T cell function and potentially aiding tumor progression." (PMID 39492834, 2024). "As an important source of energy for many tumor cells, tryptophan (Trp), is easily degraded to kynurenine (Kyn) by indolamine 2,3- dioxygenase 1 (IDO1), which activates the axis of Kyn-AHR to form special suppressive immune microenvironment that promotes tumor growth and metastasis." (PMID 38755645, 2024). "Additionally, the response to tumor cells (GO:0002834) featured CD274 and AHR genes with a fold enrichment surpassing." (PMID 38658744, 2024). "Our findings suggest that targeting the AHR could hold therapeutic potential in ccRCC; the activation of this receptor, despite the constitutive HIF1A triggering, is shown to potentiate the tumour suppressor behaviour of both the AR and RB1." (PMID 39336758, 2024). "Findings from tumor-forming mouse models indicated that the absence of AhR heightened colon carcinogenesis." (PMID 39767818, 2024). "An additional AhR inhibitor, BAY-218 (from Bayer AG, Leverkusen, Germany), stimulated pro-inflammatory monocyte and T cell responses in vitro and anti-tumor responses in vivo in tumor models using CT16 and B16-OVA cell lines." (PMID 38339226, 2024). "The 5-FU-mediated ICD effect activated the biological immune systems in tumor tissues, however, IFN-γ from T cells could re-persuade the Kyn-AHR axis activation, leading to poor efficiency of tumor treatment." (PMID 38755645, 2024). "The kynurenine-AhR pathway directly upregulates PD-1 expression on CD8+ T cells, while interferon gamma (IFNγ) expression from activated CD8+ T cells drives further kynurenine production from tumor repopulating cells, leading to paracrine deactivation." (PMID 38339226, 2024). "Recently, it was discovered that AhR binds to lncRNA and actively controls the expression of the glycolytic enzyme gene hexokinase 2 (HK2), stimulating glycolytic metabolism and accelerating tumor growth." (PMID 38434684, 2024). "Additionally, AhR signaling induces M2 TAMs to express CD155, which mediates tumor immunosuppression." (PMID 39371092, 2024). "However, the secretion of IFN-γ from effective T cell would re-establish Kyn-AHR axis based TIM, resulting in poor efficiency of tumor treatment." (PMID 38755645, 2024). "For example, the AhR-target PARP7 (product of the gene TIPARP), can directly suppress STING activity by facilitating the degradation of TBK1, a key downstream effector kinase of STING, thereby suppressing IFN-I expression and subsequent anti-tumor immunity." (PMID 38459088, 2024). "ITE, a synthetic potent agonistic ligand of AhR, has shown efficacy in reducing OCT4 levels, inducing the differentiation of stem-like cancer cells, and attenuating their tumorigenic potential in xenograft tumor models." (PMID 39211042, 2024). "It is likely that without sufficient AhR activity, anti-tumor immunity would act as a barrier to tumor formation." (PMID 38459088, 2024). "The immune cell infiltration degree in the tumor nest was not correlated with AhR expression in the tumor region for either TAMs or T cells." (PMID 38680496, 2024). "Conversely, nontoxic AhR agonists, such as Aminoflavone (AF), a dietary flavonoid, induce tumor suppressor-like qualities." (PMID 36831661, 2023).
tumor (continued). "This is exemplified by systemic cortisol/GR inducing tumor TDO and kynurenine release to activate the AhR on NK cells and CD8+ T cells, thereby driving cytolytic cell “exhaustion”, whilst altering the dynamic metabolic interactions and behaviors of tumor microenvironment cells." (PMID 37970210, 2023). "Consistently, AhR and β-catenin staining was only observed in the tumor cells of ApcMin/+ mice, but not in the lamina propria cells of ApcMin/+ AhR -/- mice." (PMID 37781044, 2023). "Moreover, we found that AHR inhibition or knockout led to decreases in p-PYGL and NADPH/NADP+ ratios and increased ROS levels in the DRCs, as well as smaller tumor sizes and prolonged survival of the mice." (PMID 38099490, 2023). "More importantly, Interleukin-4-induced-1 (IL4I1) as a metabolic immune checkpoint, activates the Aryl hydrocarbon receptor (AHR), circumvents Immune Checkpoint Blockade (ICB) and further elicits major effects in immunosuppression shaping tumor microenvironment." (PMID 37221577, 2023). "Consistently, we found that ROS and NADPH levels were lower and higher, respectively, in the resistant tumor cells, compared with the control unresistant cells, which were further enhanced by DDP treatment, concomitant with AHR sulfenylation and colocalization with PTG of the glycogen complex." (PMID 38099490, 2023). "AhR, which—just as HIF-1α—belongs to the bHLH/PAS family of transcription factors, is important both for normal cell physiological processes and for tumor progression because AhR partakes in the molecular cascades that inhibit cell proliferation, differentiation, and apoptosis." (PMID 37305351, 2023). "Taken together, we observe a negative correlation between overall HIF and AHR transcriptional activation in ccRCC tumours from the TCGA-KIRC cohort." (PMID 36725335, 2023). "This immune suppressive axis could be an effective target by selective blockade of AhR to delay the progression of IDO/TDO overexpressing tumors and enhance anti-tumor efficacy when combined with immune checkpoint blockade." (PMID 37277776, 2023). "However, like AHR, HIF can be both pro- and anti-tumourigenic depending upon the setting, and in ccRCC, HIF-2 promotes tumour growth, whereas HIF-1 is tumour suppressive." (PMID 36725335, 2023). "Further studies are needed to evaluate whether AhR signaling can maintain attenuated TRAIL activity and tumor progression after PH even if TRAIL activity and cytotoxicity of lr‐NK cells are reduced in NAFLD and NASH models." (PMID 37747052, 2023). "Recently, it has been proved that the trigger of tryptophan-kynurenine-aryl hydrocarbon receptor pathway could lead to programmed cell death protein 1 (PD-1) upregulation in CD8+ T cells and damage their killing effects on tumors in the tumor microenvironment." (PMID 37040510, 2023). "Within the THCA patient subgroup, TET3 and AHR expression levels were significantly lower in the tumor normal subgroup compared to the tumor grade 1/2/3/4 subgroups." (PMID 37718440, 2023). "Using WT and AHR−/− tumor cell models, we observed that TET3 could bind to AHR, and this binding can be disrupted by AHR-specific siRNA." (PMID 37718440, 2023). "In addition, AhR inhibition by SR1 downregulated Cyp1a1, Cyp1b1 and Runx1 expression in MEPs in tumor-bearing mice." (PMID 37919525, 2023). "In addition, in a series of tumor cell lines, IDO1 expression was shown to be driven by an autocrine positive feedback loop via the activation of AhR by kynurenine." (PMID 36422996, 2023). "In some cancers, it has been shown that AHR activation can contribute to the upregulation of PD1 and PDL1 expression in immune cells, such as T lymphocytes and monocytes, leading to immune suppression and tumour immune evasion." (PMID 37760608, 2023). "In addition, numerous experiments have demonstrated that tumor cells expressing IDO can suppress immune cells through tryptophan starvation and that AhR is involved in tumor immune escape." (PMID 37924140, 2023).